Y_RNA (Y RNA )
Gene: Miscellaneous RNA gene on chromosome 1 (38,950,825 to 38,950,925, reverse strand). Ensembl gene ENSG00000207466.
Homologues: Orthologues: chimpanzee Y_RNA (99% identical), macaque Y_RNA (94% identical). Paralogues in human: RNY3 (88% identical), Y_RNA (88% identical), RNY3P1 (87% identical), Y_RNA (87% identical), Y_RNA (86% identical), Y_RNA (85% identical), RNY3P14 (84% identical), Y_RNA (84% identical), RNY3P5 (83% identical), RNY3P7 (83% identical), Y_RNA (83% identical), RNY3P2 (82% identical), and 92 more.